IL22 (interleukin 22)
Diseases named in the same sentence as IL22 in open-access papers (continued):
Sharing a sentence is not in itself a finding about the gene and the disease.
lung carcinoma (continued). "Coincidently, a recent study reported that IL-22 could upregulate CD155 expression in breast and lung cancer cells." (PMID 38596684, 2024). "In general, blocking vascular cell adhesion molecule-1 (VCAM-1) by siRNA138 and inhibiting IL-22 with an anti-IL-22 antibody, CAF-CM-promoted proliferation was attenuated via factors downstream of PI3K/AKT signaling cascade in the same type of lung cancer." (PMID 34108441, 2021). "Increased expression of IL-22 and its receptor IL-22R1 and increased activation of STAT3 in human lung cancer cell lines mediate resistance to standard chemotherapy, which could be linked to the role of IL-22 in induction of stemness properties." (PMID 32039025, 2019). "Moreover, up-regulation of IL-22 promotes tumor proliferation via the AKT signaling pathway and induces chemotherapy resistance in human lung cancers." (PMID 31750252, 2019). "Evidence has shown that IL-22 has a crucial effect on non-melanoma skin cancer cell proliferation and the metastasis of colon and lung cancers." (PMID 29262587, 2017). "In patients with lung cancer, IL-22 levels in lavage did not correlate with systemic signs of inflammation." (PMID 27388918, 2016). "In the present study, we did not detect IL-22 in BAL samples from some of the lung cancer patients studied." (PMID 27388918, 2016). "IL-6, IL-22, and VEGF have also been detected in pleural effusion and lung cancer tissue." (PMID 27445423, 2016). "This suggests that IL-22 in the lavage of lung cancer patients reflects local processes in the lung rather than systemic inflammation." (PMID 27388918, 2016). "Patients with bacterial pneumonia, lung cancer or pulmonary manifestations of other tumours appear to have higher levels of IL-22 in lavage samples compared with non-lung disease controls." (PMID 27388918, 2016). "With regard to IL-22, several studies have showed that high expression concentrations of IL-22 were detected in tumor tissue, MPE, and serum of patients with lung cancer and that the overexpression of IL-22 was correlated with occurrence and progress of lung cancer." (PMID 24872958, 2014). "Conclusively, the present results confirm that Th22 cells/IL-22 may serve as a negative immune regulator in lung cancer." (PMID 35669104, 2022). "Furthermore, IL-22 upregulates the phosphorylation level of JNK in the pemetrexed-resistant A549 cell line, and this may be one of the mechanisms that promote the resistance of lung cancer cells to pemetrexed." (PMID 35669104, 2022). "Recently, interleukin 22 (IL22), an immune molecule secreted mostly by CD4+ T cells, was reported having functions in a variety of human diseases including encouragement of lung cancer progression, yet, its role in CM is lacking." (PMID 32201538, 2020). "IL-22 expression was consistently overexpressed in recurrent NSCLC tissue and serum, and promoted cellular proliferation and migration of tumor cells; however, this elevation did not reveal correlation with prognosis of lung cancer patients." (PMID 30473538, 2018).
lung fibrosis (35 papers, 2011 to 2025). "IL-22 mediated an anti-fibrogenesis effect in the bleomycin-induced pulmonary fibrosis model and this effect was associated with inhibition of IL-17A." (PMID 36564791, 2022). "In conclusion, we found IL-22 mediated an anti-fibrogenesis effect in the bleomycin-induced pulmonary fibrosis model and the effect associated with inhibition of IL-17A." (PMID 36564791, 2022). "For example, IL-22-deficient mice showed a significant reduction of lung inflammation and pulmonary fibrosis after high dose bleomycin treatment compared with IL-22-sufficient mice." (PMID 33407883, 2021). "The cause and effect of IL‐22 in the protection against pulmonary fibrosis have been established by using an IL‐22R KO mouse model and an IL‐22 protein augmentation model via intranasal instillation of recombinant IL‐22." (PMID 34459137, 2021). "Preventing expression of IL-22 by mutating the aryl hydrocarbon receptor (AhR)—or inhibiting AhR signaling—accelerated lung fibrosis." (PMID 27824548, 2016). "Blockade of IL-22 deteriorated pulmonary fibrosis, and was associated with elevated α-smooth muscle actin and overactivated Smad2." (PMID 27824548, 2016). "Decrement of IL-22 level, either secreted or in situ, implicated a potential role of IL-22 in pulmonary fibrosis." (PMID 23476100, 2013). "To further explore the underlying mechanism of IL-22 in BLM-induced pulmonary fibrosis, we examined IL-22 expression in the lung." (PMID 23476100, 2013). "By this rigorous study design, we have for the first time demonstrated the inverse relationship between IL‐22 expression and disease severity of IPF in the clinical cohort, and established the causal role of IL‐22 in the protection against pulmonary fibrosis by inhibiting the TGFβ pathway." (PMID 34459137, 2021). "Moreover, in a SSc mouse model, a significant reduction of lung inflammation and pulmonary fibrosis was observed in the IL-22-deficient mice after they received high doses of bleomycin, indicating a pathogenic aspect of IL-22 in SSc." (PMID 33407883, 2021). "Our studies revealed a close association between IL-22 and pulmonary fibrosis." (PMID 23476100, 2013). "In the context of pulmonary fibrosis, emerging evidence also points to a protective role for IL-22, particularly through its effects on epithelial cells." (PMID 40607394, 2025). "Further research is needed to elucidate the specific pathways through which IL-22 influences lung fibrosis and to assess its therapeutic potential in this context." (PMID 40607394, 2025). "A mouse model study reported that bleomycin-induced lung fibrosis leads to a decrease in IL-22, and administering exogenous IL-22 can inhibit the inflammatory and fibrotic process." (PMID 37753072, 2023). "In this study, we investigated the role of IL-22 on bleomycin-induced pulmonary fibrosis and the possible interaction between IL-22 and IL-17A." (PMID 36564791, 2022). "Mechanistically, IL-22 reduced the Th17 cell proportion and IL-17A mRNA level in lung tissues, and treatment with an IL-17A neutralizing antibody alleviated the severe pulmonary fibrosis in IL-22 knockout mice." (PMID 36564791, 2022). "IL-22 knockout mice showed aggravated pulmonary fibrosis compared with wild-type mice, and injection of recombinant IL-22 decreased the severe fibrotic manifestations in IL-22 knockout mice." (PMID 36564791, 2022). "Administration of IL-22 alleviates lung fibrosis, while inhibition of IL-22 leads to increased collagen accumulation in the lungs." (PMID 35967401, 2022). "IL-17A induces the aggregation of inflammatory cells and the release of inflammatory factors, which promotes the development of pulmonary fibrosis, while IL-22 protects epithelial cells and plays an anti-fibrotic role." (PMID 36564791, 2022). "We investigated the role of IL-22 on bleomycin-induced pulmonary fibrosis and the mechanism in the possible interaction between IL-22 and IL-17A." (PMID 36564791, 2022).
lung fibrosis (continued). "IL-22KO mice showed aggravated pulmonary fibrosis compared with WT mice, and injection of recombinant IL-22 reversed the severe fibrotic manifestations in IL-22KO mice." (PMID 36564791, 2022). "Conversely, IL-22 produced by γδ T cells was shown to protect against lung fibrosis, using a mice model induced by hypersensitivity to Bacillus subtilis." (PMID 33407883, 2021). "For example, the protective role of γδ T‐cell‐derived IL‐22 in pulmonary fibrosis has first been shown in a hypersensitive pneumonitis model induced by repeated exposure to Bacillus subtilis." (PMID 34459137, 2021). "Deficiency of γδTCR or inhibition of AhR signaling aggravated lung fibrosis, which was restored by nasal inhalation of recombinant IL-22." (PMID 32708044, 2020). "Vγ6Vδ1 γδ T cells are the predominant source of IL-22 in protecting the lung from pulmonary fibrosis." (PMID 32676074, 2020). "For example, Helicobacter-induced increased IL-22 expression protects mice from acute pancreatitis, and IL-22 mediates the protective effect of γδ T cells in lung fibrosis." (PMID 30159338, 2018). "Our findings are consistent with the suppression of CXCL-9 by IL-22 in an animal model of lung fibrosis which limited recruitment of CD4+CXCR3+ T cells and attenuation of lung inflammation and fibrosis." (PMID 29163483, 2017). "Alternatively, lung fibrosis in asthmatic patients depends on TGFβ, which promotes secretion of interleukin 22 (IL-22), synergizing with TGFβ to promote EMT in bronchial epithelial cells." (PMID 27367735, 2016). "Other studies have found that loss of γδ T cells enhances lung fibrosis, through loss of the anti-fibrotic mediators CXCL10, IL-22, and IFN-γ." (PMID 27649073, 2016). "In that study, IL-22 protects against lung fibrosis by suppressing the CXCL9-dependent recruitment of CD4+ T cells into the lung." (PMID 27650379, 2016). "Namely, inhibition of IL-22 resulted in enhanced collagen deposition in the lung, whereas treatment with recombinant IL-22 inhibited lung fibrosis." (PMID 26199463, 2015). "These beneficial antifibrotic effects of IL-22 suggest its potential as a novel therapeutic target in the treatment of pulmonary fibrosis." (PMID 26199463, 2015). "For instance, Liang and colleagues reported that IL-22 inhibited the development of bleomycin-induced pulmonary fibrosis." (PMID 26504852, 2015). "In the present study, we investigated the role of IL-22 in EMT in BLM-induced pulmonary fibrosis mouse model as well as in vitro." (PMID 23476100, 2013). "Strikingly, the BLM-induced pulmonary fibrosis was much worse after the IL-22 neutralizing Ab treatment as compared with the isotype Ab-control, shown by H&E and Masson's trichrome-stained lung sections." (PMID 23476100, 2013). "We found that IL-22 inhibited BLM-induced EMT, suggesting a potential therapeutic role of IL-22 in pulmonary fibrosis." (PMID 23476100, 2013). "Taken together, our studies identified IL-22 as a critical regulator of pulmonary fibrosis after BLM administration, implicating the potential utility of IL-22 in the treatment of pulmonary fibrosis." (PMID 23476100, 2013). "Here we investigated the effect of IL-22 on alveolar epithelial cells in the bleomycin- (BLM-) induced pulmonary fibrosis." (PMID 23476100, 2013). "Blockade of expression of IL-22 accelerated lung fibrosis, whereas administration of recombinant IL-22 inhibited lung fibrosis." (PMID 23374544, 2013). "On the other hand, protection mediated by IL-22 produced by gamma/delta T cells has been reported in a mouse model of lung fibrosis induced by hypersensitivity to Bacillus subtilis." (PMID 21996293, 2011). "Therefore, we evaluated the lung collagen deposition in the infected lung tissue, and both IL-23 and IL-22 absence resulted in a more intense lung fibrosis compared to the WT group." (PMID 39635124, 2024). "In this study, we explored the impact of IL-22 on pulmonary fibrosis both in vivo and in vitro." (PMID 36564791, 2022).
lung fibrosis (continued). "In that study, IL‐22 inhibition enhanced collagen deposition while treatment with recombinant IL‐22 inhibited lung fibrosis, suggesting that IL‐22 might be protective." (PMID 34459137, 2021). "Also, in pulmonary fibrosis, IL-22 (an anti-inflammatory cytokine of the IL-10 family) exerts an anti-fibrotic effect via inhibiting EMT by targeting alveolar epithelia, which is the only target cell type of IL-22 in the lung." (PMID 33723241, 2021). "IL‐22 appears to be protective against pulmonary fibrosis by inhibiting TGF‐β1 signaling, and IL‐22 augmentation may be a promising approach to treat IPF." (PMID 34459137, 2021). "This notion has been further supported by evidence from more relevant bleomycin (BLM) induced lung fibrosis model, in which treatment with anti‐IL‐22 neutralizing antibody exacerbated airway inflammation and enhanced expressions of a number of fibrotic biomarkers." (PMID 34459137, 2021). "We suggested that IL‐22 appears to be protective against pulmonary fibrosis by inhibiting TGF‐?1 signaling, and IL‐22 augmentation may be a promising approach to treat IPF." (PMID 34459137, 2021). "IL-22 also contributes to the inhibition of pulmonary fibrosis." (PMID 32676074, 2020). "IL-22 prevents experimental lung fibrosis, airway inflammation and tissue damage." (PMID 31809521, 2019). "However, the evidence of lung fibrosis needs to be supplied, and more functional details of IL-22 in the development of BLM induced lung fibrosis need further study." (PMID 23476100, 2013). "Furthermore, blockage of IL-22 deteriorated pulmonary fibrosis, with elevated EMT marker (α-smooth muscle actin (α-SMA)) and overactivated Smad2." (PMID 23476100, 2013). "In the previously reported mouse model of hypersensitivity pneumonitis, the authors found that IL-22-secreting γδT cells could protect from lung fibrosis by diminishing recruitment of CD4+T cells to the lung." (PMID 23476100, 2013). "We think that IL-22 may play a protective role in pulmonary fibrosis through inactivating TGF-β/Smad signaling." (PMID 23476100, 2013). "Our results indicate that IL-22 may play a protective role in the development of BLM-induced pulmonary fibrosis and may suggest IL-22 as a novel immunotherapy tool in treating pulmonary fibrosis." (PMID 23476100, 2013). "Since substitute rhIL-22 could ameliorate BLM-induced EMT, we suspect that blockage of IL-22 may deteriorate BLM-induced lung fibrosis." (PMID 23476100, 2013). "Another study described how IL-17A may regulate the expression and/or proinflammatory properties of IL-22 in pulmonary fibrosis but did bot analysed the link between IL-1β, IL-23and IL-17." (PMID 21858022, 2011). "Moreover, IL-22 can also prevent pulmonary fibrosis in a Bacillus subtilis induced model." (PMID 35967401, 2022). "IL-22 may serve as a potential target for intervening pulmonary fibrosis." (PMID 36564791, 2022). "Furthermore, clinical evidence linking IL‐22 and pulmonary fibrosis is still scarce." (PMID 34459137, 2021). "The action of IL-22 may well be modified by IL-17, as demonstrated in lung fibrosis." (PMID 24587305, 2014). "And we found that IL-22 mainly produced γδT cells were decreased significantly both in the lung and spleen at the 3rd week, indicating TCRγδ+IL-22+ cell may participate in the regulation of pulmonary fibrosis." (PMID 23476100, 2013). "Thus, the ability of IL-22 to regulate BLM-induced pulmonary fibrosis both in vivo and in vitro raises the possibility that IL-22 may act as a potential target to treat diseases characterized by chronic lung inflammation and fibrosis." (PMID 23476100, 2013). "Administration of an anti-IL-22 neutralizing antibody has also been shown to enhance pulmonary inflammation and ECM deposition in the same bleomycin-induced model of lung fibrosis." (PMID 26199463, 2015). "To date, however, the crosstalk between IL-22 and TGF-β-driven EMT in pulmonary fibrosis has remained unclear." (PMID 23476100, 2013).
lung fibrosis (continued). "Taken together, these data provide the evidence that IL-22 regulates the process of BLM-induced EMT and pulmonary fibrosis, likely via TGF-β/Smad2 signaling pathway." (PMID 23476100, 2013). "Hence, γδT cells may play the critical role as an inhibitor of pulmonary fibrosis via IL-22." (PMID 23476100, 2013). "To determine in vivo function of IL‐22, we utilized BLM induced mouse model of pulmonary fibrosis." (PMID 34459137, 2021). "In a mouse model of BLM‐induced lung fibrosis, the lack of IL‐22 signaling exacerbated and IL‐22 augmentation prevented inflammation and fibrogenesis, supporting the protective function of IL‐22." (PMID 34459137, 2021). "Overall, these data provide evidence that IL‐22 augmentation by intranasal instillation could repress the TGF‐β pathway and BLM‐induced pulmonary fibrosis." (PMID 34459137, 2021). "Obese Nod2−/− mice had higher inflammatory cell infiltration in the bronchial alveolar lavage (BAL) and lungs, pulmonary fibrosis, mucus levels, hypertrophy and hyperplasia of goblet cells, M2 alveolar macrophage infiltration, interleukin-4 (IL-4), IL-5, IL-6, and lower CXCL1 and IL-22." (PMID 39507249, 2024). "Indeed, it has been demonstrated that recombinant IL-22 treatment inhibits the phenoconversion of alveolar epithelial cells into MFs, thus reducing the number of ECM producing cells in a bleomycin-induced mouse model of lung fibrosis." (PMID 26199463, 2015). "In the present study, we investigated a BLM-induced pulmonary fibrosis model for 8 weeks and found a progressive process of EMT, aberrant reepithelization, ultimate deposition of ECM, and destruction of lung architectures, accompanied by significantly decreased production of IL-22." (PMID 23476100, 2013). "Thus, IL‐22 function in the mouse model of pulmonary fibrosis has not been completely defined." (PMID 34459137, 2021).